SLC35A1 (solute carrier family 35 member A1)
Description:
Transports CMP-sialic acid from the cytosol into the Golgi apparatus, functioning as an antiporter that exchanges CMP-sialic acid for CMP. Binds both CMP-sialic acid and free CMP, but has higher affinity for free CMP (By similarity). Also able to exchange CMP-sialic acid for AMP and UMP. Also mediates the transport of CDP-ribitol (By similarity).
Synonyms: CMP-Sia-Tr; CST; CMPST; hCST; CDG2F
Tractability: Antibody: its Gene Ontology location is reachable by antibodies, with high confidence; UniProt predicts a signal peptide or a membrane-spanning region. PROTAC: ubiquitination databases record sites on it; its protein half-life has been measured.
Gene: Protein-coding gene on chromosome 6 (87,470,623 to 87,512,336, forward strand). Ensembl gene ENSG00000164414.
Subcellular location: Golgi apparatus membrane; Golgi apparatus
Pathways (Reactome):
Disease: Defective SLC35A1 in sialic acid metabolism causes congenital disorder of glycosylation 2F (CDG2F); Defective transport by SLC35A1 causes congenital disorder of glycosylation 2F (CDG2F)
Metabolism of proteins: Matriglycan biosynthesis on DAG1; Sialic acid metabolism
Transport of small molecules: Transport of nucleotide sugars
Gene Ontology:
Molecular function: protein binding; antiporter activity; CMP-N-acetylneuraminate transmembrane transporter activity; pyrimidine nucleotide transmembrane transporter activity; pyrimidine nucleotide-sugar transmembrane transporter activity
Biological process: CMP-N-acetylneuraminate transmembrane transport; carbohydrate metabolic process; protein modification process; protein O-linked glycosylation; N-acetylneuraminate metabolic process; nucleobase-containing compound transport; organophosphate ester transport; pyrimidine nucleotide transport; pyrimidine nucleotide-sugar transmembrane transport
Cellular component: Golgi apparatus; Golgi membrane; membrane; plasma membrane
Genetic constraint (gnomAD): Loss-of-function variants: 16 observed, 35.66 expected, observed/expected ratio (o/e) 0.45, 90% interval 0.3 to 0.68. The upper end of that interval is the gene's LOEUF score, 0.68, which puts it in group 2 of 6, group 1 being the genes least tolerant of losing a copy. Missense variants: 280 observed, 386.55 expected, observed/expected ratio (o/e) 0.72, 90% interval 0.66 to 0.8. Synonymous variants: 140 observed, 153.17 expected, observed/expected ratio (o/e) 0.91, 90% interval 0.8 to 1.05.
Gene-disease validity (ClinGen):
ClinGen rates the evidence that SLC35A1 causes each of these diseases.
SLC35A1-congenital disorder of glycosylation (autosomal recessive): Moderate. SLC35A1-CDG is an extremely rare form of CDG syndrome characterized clinically in the single reported case by repeated hemorrhagic incidents, including severe pulmonary hemorrhage.
Homologues: Orthologues: chimpanzee SLC35A1 (100% identical), macaque SLC35A1 (98% identical), pig SLC35A1 (94% identical), dog SLC35A1 (94% identical), guinea pig SLC35A1 (93% identical), mouse Slc35a1 (91% identical), rat Slc35a1 (91% identical), tropical clawed frog slc35a1 (80% identical), zebrafish slc35a1 (76% identical), Caenorhabditis elegans ugtp-1 (36% identical). Paralogues in human: SLC35A2 (44% identical), SLC35A3 (38% identical), SLC35A5 (24% identical), SLC35A4 (22% identical).
Diseases named in the same sentence as SLC35A1 in open-access papers:
SLC35A1 is named in the same sentence as 24 diseases in open-access papers, as found by Europe PMC text mining. Sharing a sentence is not in itself a finding about the gene and the disease. The quoted sentences say what the papers report.
Thrombocytopenia (4 papers, 2021 to 2025). A reduction in the number of circulating thrombocytes. "Therefore, it is expected that molecular alterations in ST3GAL4 are associated with a phenotype similar to that observed in patients with SLC35A1-RD, where platelets have an increased clearance from bloodstream, leading to thrombocytopenia." (PMID 36982178, 2023). "The phenotype of the patients with genetic alterations in GNE, SLC35A1, GALE and B4GALT is consistent with syndromic manifestations, severe inherited thrombocytopenia, and hemorrhagic complications." (PMID 36982178, 2023). "Thrombocytopenia with impaired megakaryocyte maturation and increased platelet clearance was also observed in a mouse model lacking Slc35a1 in megakaryocytes and platelets." (PMID 40613041, 2025).
viral infection (4 papers, 2019 to 2025). "Results from the screen and subsequent analysis highlighted that several genes involved in sialic acid synthesis, including ST3GAL4, ST6GAL1, and SLC35A1, are important for viral infection." (PMID 40767522, 2025). "Both genes identified, SLC30A1 and SLC35A1, represent novel host factors that affected the induction of apoptosis upon viral infection." (PMID 31320712, 2019). "Altogether, these data suggest the decreased viability of cells lacking SLC35A1 after viral infection arises from a combination of a more pronounced apoptotic response and an increased rate of VSV replication." (PMID 31320712, 2019). "Furthermore, genetic screening using the cytolytic vesicular stomatitis virus (VSV) also found that deletion of the SLC35A1/CMP-sialic transporter was involved in the apoptotic response generated by VSV, providing new information about the cellular response to oncolytic viral infections." (PMID 34944621, 2021).
colorectal cancer (2 papers, 2021 to 2025). A primary or metastatic malignant neoplasm that affects the colon or rectum. "Our study showed downregulation of SLC35A1 expression in various tumors, including colorectal cancer, compared to adjacent normal tissues." (PMID 40303483, 2025). "Indeed, a small-molecule inhibitor of SLC35A1 has been shown to reduce cell surface sialylation and inhibit the metastasis of human colorectal cancer cells within a mouse model." (PMID 34384782, 2021).
congenital disorder of glycosylation (2 papers, 2025). Congenital disorder of glycosylation (CDG) is a fast growing group of inborn errors of metabolism characterized by defective activity of enzymes that participate in glycosylation (modification of proteins and other macromolecules by adding and processing of oligosaccharide side chains). "SLC35A1-CDG is a very rare type of congenital disorders of glycosylation (CDG) with only five cases known to date." (PMID 40613041, 2025).
Macrothrombocytopenia (2 papers, 2025). "However, natural mutations in SLC35A1 were linked to the development of macrothrombocytopenia and neutropenia in humans, and endothelial-specific knockout of SLC35A1 in mice resulted in excessive hepatic lipid accumulation and increased mortality." (PMID 40586559, 2025). "Based on the described SLC35A1-CDG patients, we define seizures, microcephaly, ataxia, developmental delay, and macrothrombocytopenia as the more common clinical characteristics of this type of disease and add café-au-lait spot, ear tag, and umbilical hernia as possibly new associated phenotypes." (PMID 40613041, 2025).
melanoma (2 papers, 2016 to 2025). A malignant, usually aggressive tumor composed of atypical, neoplastic melanocytes. "To investigate the influence of tumor-expressed sialic acids on anti-tumor immunity we reduced their presence on the hyper-sialylated cell surface of murine B16 melanoma by knockdown of the Slc35a1 gene encoding the Golgi-based CMP-sialic acid transporter." (PMID 26741508, 2016). "SLC35A1 knock-down in B16 melanoma reduced tumor growth due to the reduction of sialylation and enhanced effector T cell response." (PMID 40718829, 2025).
aspartylglucosaminuria (1 paper, 2021). Aspartylglycosaminuria (AGU) is an autosomal recessive lysosomal storage disease belonging to the oligosaccharidosis group (also called glycoproteinosis). "To test the suitability of the SLC35A1 knockout cells for a potency assay, we used an AAV9 vector (AAV9/AGA) that carries the optimized human AGA gene coding for aspartylglucosaminidase (AGA) that is deficient in aspartylglucosaminuria (AGU)." (PMID 34069698, 2021).
chromophobe renal cell carcinoma (1 paper, 2020). Chromophobe renal cell carcinoma is a rare subtype of renal cell carcinoma, originating from the intercalating cells of the collecting ducts and macroscopically manifesting as a well-circumscribed, highly lobulated, solid tumor that is usually diagnosed at an early stage. "For example, high SLC35A1 expression is favorable for clear cell renal carcinoma but unfavorable for papillary and chromophobe renal cell carcinoma." (PMID 32599841, 2020).
Failure to thrive (1 paper, 2025). Failure to thrive (FTT) refers to a child whose physical growth is substantially below the norm. "In addition to known clinical symptoms of SLC35A1-CDG, the patient presents with failure to thrive, short stature, café-au-lait spot, and preauricular ear tag." (PMID 40613041, 2025).
glycosylation disorder (1 paper, 2025). "Here, we report the sixth patient with a novel missense variant in SLC35A1 and provide a comprehensive summary of all known cases, aiming to raise awareness of this rare glycosylation disorder." (PMID 40613041, 2025). "SLC35A1-CDG stands out as one of the very rare glycosylation disorders, with only six reported cases to date, including the newly described patient." (PMID 40613041, 2025).
lung adenocarcinoma (1 paper, 2025). A carcinoma that arises from the lung and is characterized by the presence of malignant glandular epithelial cells. "We found that CMAS and SLC35A1 correlated with worse survival outcomes in lung adenocarcinoma." (PMID 40718829, 2025).
lung squamous cell carcinoma (1 paper, 2025). "Notably, SLC35A1 was also seen to be associated with worse survival outcomes in lung squamous cell carcinoma." (PMID 40718829, 2025).
reovirus infection (1 paper, 2022). "These hits include SLC35A1 and CTSL, whose gene products are required for reovirus infection." (PMID 35320319, 2022).
infection (14 papers, 2019 to 2025). The state of being infected such as from the introduction of a foreign agent such as serum, vaccine, antigenic substance or organism. "To assess how SA deficiency affects post-attachment infection stages, we evaluated GCRV-I replication in GNE/SLC35A1 knockdown cells." (PMID 40911632, 2025). "Solute carrier family 35 member A1 (SLC35A1), a key component in the sialic acid (SA) synthesis pathway, was identified as a necessary host factor for the infection of swine enteric CoVs, including SADS-CoV." (PMID 39858149, 2025). "We then used a SeV reporter virus expressing eGFP (rSeVCeGFP) to directly assess the impact of SLC35A1 or SLC35A2 during infection." (PMID 39253522, 2024). "The infection titer in the culture supernatants was also reduced in the SLC35A1 KO, SLC35A2 KO, or Triple KO cells." (PMID 37819933, 2023). "Inactivation of SLC35A1 in HeLa cells inhibits infection by VSV-LCMV and VSV expressing the glycoproteins of PIV5 (VSV-PIV5), a paramyxovirus that uses sialic acid as entry receptor." (PMID 35235462, 2022). "Functional ablation of the CMP–sialic acid transporter by SLC35A1 gene knockout provides means for increasing the infection efficiency by AAV9 in cell lines that divide rapidly." (PMID 34069698, 2021). "Genetic screens with the cytolytic vesicular stomatitis virus (VSV) showed that the loss of two SLCs genes, encoding the sialic acid transporter SLC35A1/CST and the zinc transporter SLC30A1/ZnT1, affected cell survival upon infection." (PMID 31320712, 2019). "The fTfR-5J8 receptor rescued infection to ~70% of Ca’09 WT infection in the Slc35A1 KO HEK cells." (PMID 40207931, 2025). "Finally, we detected significantly increased virus titers in SLC35A1 knockout cells compared to wild type cells following a single infection cycle, as measured by FACS, suggesting increased rates of viral replication." (PMID 31320712, 2019). "Notably, the rescue of infection was comparable to that observed in SLC35A1-reconstituted cells." (PMID 40207931, 2025). "The solute carrier family 35 member A1 (SLC35A1) and the VPS35 endosomal protein sorting factor like (VPS35L) were identified as a host factors required for PDCoV infection." (PMID 41465565, 2025). "Slc35a1 KO led to complete resistance to MVM infection, while Mgat1 and Cosmc KO led to significant inhibition of infection." (PMID 37175850, 2023). "Infection of A549 cells with a recombinant LCMV-Armstrong engineered to express GFP, LCMV-2A-GFP, also show a marked reduction in infection upon inactivation of CD164, ST3GAL4, or SLC35A1." (PMID 35235462, 2022). "Collectively, these data directly demonstrate a role of CD164, SLC35A1, and ST3GAL4 in LCMV-GP–mediated infection at the entry step and validate their importance for infection with WT LCMV." (PMID 35235462, 2022). "As expected, SLC35A1 knockout (KO) cells showed drastic reduction in infections with SeV, NDV and MuV due to the lack of cell surface sialic acids receptors." (PMID 39792924, 2025). "As expected, our results show that the fTfR-5J8 receptor did not rescue infection of PR8 HEK Slc35A1 KO cells." (PMID 40207931, 2025). "SLC35A1 knockout (KO) cells showed significantly reduced binding and infection of SeV, NDV and MuV due to the lack of cell surface sialic acids, which act as their receptors." (PMID 39253522, 2024). "Using a LCMV-pseudotyped virus and an infection period of 3 weeks, the authors identified seven host factors important for LCMV entry, four of which (CD164, ST3GAL4, SLC35A1, and MAN1A2) were contained within the set of 37 factors identified in our live virus screen." (PMID 35502904, 2022). "Cells transiently reconstituted by expression of Slc35A1 from a plasmid displayed similar levels of IAV infection to HEK WT cells, while no Ca’09 infection was detected in the control fTfR-expressing cells." (PMID 40207931, 2025).
tumor (13 papers, 2016 to 2025). "Therefore, it is worthwhile to investigate how the altered salivary acidification caused by SLC35A1 affects immune cell activity in the tumor microenvironment." (PMID 40303483, 2025). "Slc35A1 has been demonstrated to improve effector T cell response, decrease the amount of 2,6-linked sialic acids on the cell surface, and boost the inflow and activity of natural killer (NK) cells, strengthening anti-tumor immunity and slowing tumor progression." (PMID 36547200, 2022). "By comparing methylation levels between tumor and normal tissues, we observed a higher methylation level in the SLC35A1 promoter in tumor tissues." (PMID 40303483, 2025). "Nevertheless, in other cancers related to the digestive system, such as the tongue, esophagus, stomach, and pancreas, SLC35A1 exhibited higher expression in tumor tissues." (PMID 40303483, 2025). "By using sialidase treatment, the sialyltransferase inhibitor P3-FAX, or SLC35A1 KO tumor cells to remove or prevent sialic acid expression on the surface of tumor cells, we demonstrate a notable enhancement in neutrophil-mediated killing efficacy." (PMID 38138970, 2023). "As a third approach, we generated a sialic acid transporter solute carrier family 35 member A1 knockout (SLC35A1 KO) line of the tumor cells." (PMID 38138970, 2023). "Cell surface hypersialylation benefits tumor cell growth and metastasis, making SLC35A1 an attractive target for drug design." (PMID 34384782, 2021). "We found that the sialic acid-donor synthesis pathway is particularly upregulated in PDAC, observing an increased expression of GNE, NANP and SLC35A1, suggesting a general increase of sialylation in the tumour." (PMID 33627655, 2021). "SLC35A1 demonstrated lower expression in tumor tissues compared to normal tissues, including CRC." (PMID 40303483, 2025). "Furthermore, the results confirm the involvement of SLC25A4 in the development of CRC and its silencing in all stages and the reduced expression of SLC35A1 in this tumor." (PMID 41465541, 2025). "Reduction of sialic acids on B16 cells by silencing the CMP-sialic acid transporter Slc35a1 slowed down tumor growth in vivo and promoted an anti-tumor immune response, boosting the tumor infiltration of effector T cells and decreasing the frequency of T regulatory cells." (PMID 34440905, 2021). "Additionally, we found a higher degree of DNA methylation in the SLC35A1 promoter region in tumor tissues, suggesting that the altered expression of SLC35A1 may be associated with abnormal methylation patterns." (PMID 40303483, 2025). "Similarly to sialidase treatment, the cytotoxicity against antibody-opsonized SKBR3 and A431 cells was significantly increased after P3-FAX pre-incubation of the tumor cells and by using the SLC35A1 KO cells, suggesting that tumor cell sialylation limits the efficacy of neutrophil ADCC." (PMID 38138970, 2023). "The results revealed that the expressions of SLC35A1 and SLC35A5 were negatively correlated with tumor purity (p < 0.05)." (PMID 40303483, 2025). "In contrast, the other family members, including SLC35A1, SLC35A3, SLC35A4, and SLC35A5, demonstrated lower expression in tumor tissues." (PMID 40303483, 2025). "Tumor cells highly expressed donor synthesis genes (NANS, CMAS, and the transporter SLC35A1), while the stroma showed enriched expression of sialyltransferases involved in α2-3, α2-6 and α2-8 sialylation (ST3GAL2, ST3GAL5, ST6GAL2, ST6GALNAC5, ST6GALNAC6, ST8SIA1 and ST8SIA2)." (PMID 38594506, 2024). "Neutrophil ADCC was evaluated after pre-incubation of tumor cells with P3-FAX (efficacy of the treatment was verified prior to each ADCC), or alternatively after use of the SLC35A1 KO cells." (PMID 38138970, 2023). "Furthermore, we identified a significant positive correlation between SLC35A1 expression and infiltration of CD8+ T cells, indicating that SLC35A1 may influence immune cell infiltration through tumor cell surface sialylation." (PMID 40303483, 2025).
cancer (3 papers, 2021 to 2025). A tumor composed of atypical neoplastic, often pleomorphic cells that invade other tissues. "Consequently, in our study, the Oncomine analysis among 20 types of cancer indicated that SLC35A1 was differentially expressed in a remarkable number of cases and was found to be down-regulated in BRCA." (PMID 34944621, 2021). "Another possibility of targeting NSTs for therapy is blocking SLC35A1 for treating cancer." (PMID 34384782, 2021).
neurodegenerative disease (1 paper, 2022). A disorder of the central nervous system characterized by gradual and progressive loss of neural tissue and neurologic function. "Therefore, our results suggest a downregulation of the glycan structures, derived from B3GALT4, ST3GAL2 and/or SLC35A1 genes, with ageing, a feature so far only described in neurodegenerative diseases." (PMID 36009354, 2022).
SLC35A1 also shares sentences with these, for which no sentence is quoted: Ataxia (1 paper); autoimmune disease (1); clear cell renal carcinoma (1); Congenital Disorder of Glycosylation type 2F (1); developmental delay (1); microcephaly (1); neutropenia (1).